TPO (thyroid peroxidase)
Diseases named in the same sentence as TPO in open-access papers (continued):
Sharing a sentence is not in itself a finding about the gene and the disease.
thyroid (continued). "Patients will have elevated thyroid-specific autoantibodies (Anti-TPO), elevated cerebrospinal fluid protein without pleocytosis, and abnormal electroencephalogram." (PMID 21941682, 2011). "Women with subclinical thyroid disease presented higher levels of anti-TPO than did women with normal thyroid function (P = 0.01)." (PMID 20512276, 2010). "Finally, thyroiditis and accompanying anti-TPO autoantibody positivity are conditions that should not be ignored by thyroidologists and thyroid-health providers." (PMID 39230146, 2024). "In contrast, in a retrospective analysis of patients treated with pembrolizumab at the Mayo Clinic, TPO antibodies were found to be present in 50% of the patients; however, the antibody titers were not elevated in patients who developed thyroiditis." (PMID 36909047, 2023). "Utilizing the most recent assays, antibodies (thyroid peroxidase autoantibodies, TRAb, thyroglobulin specific antibodies) are proving to be a potent marker (if not pathogen) of thyroid disorders, and the subsequent months are expected to provide further insight into its function in this state." (PMID 36514581, 2022). "Rheumatoid and thyroid autoantibodies were found in a small number of subjects, including antinuclear antibody (3/58, 5%), anti-Sjogren syndrome A antibody (SSA) (2/58, 3%), anti-thyroid peroxidase antibodies (aTPO) and/or antithyroglobulin antibodies (aTG) (5/58, 9%)." (PMID 31080435, 2019). "Finally, in non-lactating women with postpartum thyroiditis, anti-TPO and anti-TG titers were found to be inversely correlated with vitamin D levels (p < 0.001)." (PMID 28303359, 2017). "Thus, the concentration of TPO autoantibodies in CSF was very low compared to plasma in both subjects with thyroid and without thyroid disease (P = 0.007)." (PMID 26798549, 2015). "However, recommended measurements of thyroid-stimulating hormone (TSH), as well as thyroid peroxidase (TPO) and thyroglobulin (Tg) aAbs levels in T1D patients to evaluate future development of overt thyroiditis is not yet a common practice." (PMID 26192189, 2015). "Thus, the aim of this study was to search for anti-TPO and anti-Tg antibodies in CSF and assess them vis-à-vis their plasma concentrations in subjects with and without thyroid disease." (PMID 26798549, 2015). "The aim of our study was to evaluate whether serum TgAb and anti-thyroid-peroxidase antibody (TPO) positivity was also related to pre-neoplastic histological changes such as papillary-like nuclear features (PLNF) and with the presence of lymphocytic infiltrate (LI) in thyroid surgical specimens." (PMID 37370937, 2023). "Thyroid antibody testing (thyroid peroxidase antibodies and/or thyroglobulin antibodies and TSH-receptor-antibodies) was more frequent in participants with diagnosed thyroid disorders independent of medication use." (PMID 32000765, 2020). "This study evaluated women's thyroid disease symptoms, physical findings, stress levels, and thyroid stimulating hormone (TSH) levels across six postpartum months in three groups, TPO negative, TPO positive, and PPT positive women." (PMID 25405057, 2014). "Beyond the increased prevalence of Hashimoto’s thyroiditis in PCOS, available research has also investigated the presence of its characteristic autoantibodies (anti-TPO and anti-thyroglobulin (anti-TG)) in euthyroid women with PCOS or those without a diagnosis of thyroid disease." (PMID 40943118, 2025). "Regarding the relationship between TSH and anti-TPO, evidence can be found in the NHANES III, which shows that the age-related TSH levels may be independent of the level of thyroid antibodies." (PMID 32612652, 2020). "At initial phase, signs and symptoms of thyroid disease are usually absent and TSH may be normal and anti-TPO antibodies may be positive." (PMID 25788942, 2015).
thyroid (continued). "Se supplementation did not affect maternal thyroid peroxidase antibody (TPO Ab) or thyroglobulin antibody (Tg Ab) from 12 to 35 weeks of gestation but resulted in a decrease of these antibody titres from 36 weeks' gestation to 6 months' postpartum in a thyroiditis positive population." (PMID 35571749, 2022).
autoimmune disease (106 papers, 2005 to 2026). A disorder resulting from loss of function or tissue destruction of an organ or multiple organs, arising from humoral or cellular immune responses of the individual to their own tissue constituents. "An important observation from this study is the statistically significant association between anti-TPO positivity and other autoimmune diseases." (PMID 41280993, 2025). "It has also been associated with other autoimmune diseases, eosinopenia, basopenia, low total IgE, and elevated IgG against thyroid peroxidase (IgG anti-TPO)." (PMID 39483682, 2024). "Rad and Deluxe reported that postpartum thyroiditis is an autoimmune disease associated with the presence of antibodies against TPO." (PMID 39124785, 2024). "It is also known to damage the follicular and parafollicular cells of the thyroid at post mortem and probably causing autoimmune disease, which causes changes in the thyroid hormone levels and thyroid peroxidase (TPO)." (PMID 39906086, 2024). "TPO and anti-thyroglobulin antibodies were strongly associated with the presence of autoimmune disease in persons with DS/MMS (p < 0.001, 95%CI: 2.46–44.8) and DS (p < 0.001, 95%CI: 3.56–11.4) but not MMD (p = 0.44, 95%CI:0.4–35.4)." (PMID 34566869, 2021). "HT is an autoimmune disease caused by antibodies to thyroid peroxidase, thyroglobulin, and/or thyroid stimulating hormone receptors causing an antibody-dependent cellularly mediated cytotoxicity of the thyroid." (PMID 32775036, 2020). "If markers for autoimmune disease exist (e.g., TPO ab), this increases the risk also for other autoimmune diseases, such as rheumatoid arthritis, type 1 diabetes, pernicious anemia, celiac disease, and Addison’s disease." (PMID 31963883, 2020). "In men, the presence of anti-TPO was strongly associated with familial anamnesis of maternal autoimmune disease." (PMID 28349935, 2017). "This may increase susceptibility to autoimmune disorders compared to the general population, helping to explain both the higher frequency and elevated levels of anti-TPO and anti-TG antibodies observed in these patients." (PMID 40806651, 2025). "However, as we mentiond before, Graves’ disease (GD) is an organ-specific autoimmune disorder characterized by the appearance of pathogenic autoantibodies against thyroid peroxidase (TPO), thyroglobulin (Tg), and the TSH receptor (TSHR)." (PMID 23189166, 2012). "Graves’ disease (GD) is an organ-specific autoimmune disorder characterized by the loss of immunological tolerance, which is pivotal to the appearance of pathogenic autoantibodies against thyroid peroxidase (TPO), thyroglobulin (Tg), and the TSH receptor (TSHR)." (PMID 23189166, 2012). "The cause of autoimmune diseases in TS remains unclear, although there are several mechanisms that suggest a potential correlation between the X-isochromosome and increased prevalence of anti-thyroid peroxidase (TPO-Ab) antibodies." (PMID 39684648, 2024). "Importantly, the autoantibodies detected in this study, anti-tTG IgG and IgA, anti-CTD IgG, GADA, and anti-TPO IgG, have diagnostic value for common autoimmune diseases, and at least some of these may play roles in disease pathogenesis." (PMID 28349935, 2017). "HT is an autoimmune disorder characterized by chronic inflammation and the presence of autoantibodies against thyroid peroxidase (TPO) and thyroglobulin, which contribute to progressive thyroid dysfunction." (PMID 40530335, 2025). "Nevertheless, the pathogenesis of PCOS and autoimmune diseases through shared autoantibodies cannot be excluded, as indicated by the presence of anti-TPO antibodies in ovarian follicular fluid." (PMID 40943118, 2025). "Autoimmune disorders were significantly more prevalent in anti-TPO-positive patients (χ2=10.83, p<0.001)." (PMID 41280993, 2025). "A statistically significant correlation was observed between autoimmune disorders and anti-TPO positivity (p<0.001)." (PMID 41280993, 2025).
autoimmune disease (continued). "Hashimoto’s encephalopathy is a rare autoimmune disorder (2 per 100,000 population), with anti-TPO antibodies detected in up to 100% of patients and anti-Tg antibodies in approximately 48%, though antibody titers do not correlate with disease severity." (PMID 41562813, 2025). "HT is the most common autoimmune disease worldwide, characterized by chronic inflammation and circulating autoantibodies against thyroid peroxidase and Tg1." (PMID 38287080, 2024). "A survey of autoimmune diseases and autoantibodies, including anti-thyroid peroxidase antibody (anti-TPO), anti-thyroglobulin antibody (ATA), anti-mitochondrial antibody, anti-nuclear antibody, and anti-ds DNA, was negative." (PMID 36851302, 2023). "Anti-TPO antibody levels were elevated more often in PID patients with a positive family history of autoimmune diseases (p = 0.04)." (PMID 37270495, 2023). "HT is the most common autoimmune disease globally, and it is characterized by chronic inflammation, increased circulating concentrations of autoantibodies against thyroid peroxidase and thyroglobulin, and tertiary lymphoid follicle development." (PMID 36817926, 2023). "A key mechanism in many autoimmune disorders is the presence of autoantibodies, and the autoantibodies characteristic of autoimmune thyroid disease, e.g. TPO-antibodies, are more commonly found in other autoimmune diseases." (PMID 34034778, 2021). "All the patients were examined for autoimmune disease symptoms and tested for the presence of antithyroperoxidase (anti-TPO) and antithyreoglobulin (anti-TG) antibodies." (PMID 31417494, 2019). "The presence of anti-TPO IgG was assessed in the gender-stratified logistic regression model adjusted for age, maternal autoimmune disease, and occupational status (significant phenotypic parameters for anti-TPO)." (PMID 28349935, 2017). "Different from anti-TPO IgG in women, incidental finding of anti-TPO IgG in men with positive familial anamnesis of maternal autoimmune disease deserves further medical intention." (PMID 28349935, 2017). "The third limitation of the present study is that we only analyzed TPO markers as an indicator of autoimmune disease." (PMID 24592326, 2014). "Identification as an autoimmune disease follows observations that lymphocytes infiltrate the thyroid and autoantibodies against thyroglobulin, thyroid peroxidase, and (rarely) thyroid hormone stimulating receptor are found in patients with HT." (PMID 16280086, 2005). "Analysis of associated autoimmune conditions demonstrated that 36 subjects (27.7%) with elevated anti-TPO antibodies also had another autoimmune disorder, whereas none of the subjects with normal anti-TPO levels had an associated autoimmune disease." (PMID 41280993, 2025). "Although no homologies between the predicted epitopes of the NIS transporter and those of TPO and Ro60 were detected in this study, the T-cell epitopes of NIS could bind to the same HLA class II alleles that predispose to both autoimmune diseases." (PMID 41516079, 2025). "These include antibodies specific to autoimmune diseases, e.g., anti-thyroid peroxidase (anti-TPO), anti-thyroglobulin (anti-TG), and antinuclear antibodies (ANAs), as well as those that are non-specific, such as anti-malondialdehyde-modified human serum albumin (anti-HSA-MDA) or anti-α-crystallin." (PMID 40943118, 2025). "Antibodies against thyroid peroxidase (TPO) were common and were found across autoimmune diseases." (PMID 38833310, 2024). "High-risk patients include women over the age of 60, pregnancy, patients with a prior history of head and neck irradiation, patients with autoimmune disorders and/or type 1 diabetes, family history, positive thyroid peroxidase antibodies, and medication adverse effects." (PMID 39967991, 2024).
autoimmune disease (continued). "The risk is higher in women over the age of 60, pregnancy, patients with a prior history of head and neck irradiation, patients with autoimmune disorders and/or type 1 diabetes, family history, positive thyroid peroxidase antibodies, and medication adverse effects." (PMID 39967991, 2024). "We successfully developed an in-house ELISA for population-level research to assess whether an individual is positive for TPO-Ab, a biomarker of autoimmune disease, based on measurement of TPO-Ab levels in a single 3-mm DBS punch." (PMID 32678000, 2020). "Autoimmune disease history was found in two of the 28 patients who tested positive for anti-TPO Ab." (PMID 25653881, 2015). "Poor response correlates with advanced age, high BMI, comorbid autoimmune diseases, low total IgE (<40–50 IU/ml), positivity for ANA or anti-TPO antibodies, and activation markers such as CD203c." (PMID 41602870, 2026). "This review assessed the prevalence and impact of thyroid-specific autoantibodies, notably anti-thyroid peroxidase (anti-TPO), anti-thyroglobulin (anti-Tg), and TSH receptor antibodies in patients with multiple autoimmune diseases." (PMID 41268326, 2025). "Given the higher presence of anti-TPO and anti-GAD antibodies, the results also highlight the need of screening for related autoimmune diseases." (PMID 40650029, 2025). "Additional non-lymphoid genes included parathyroid receptor 2 (PTHR2) and thyroid peroxidase (TPO), both of which have been connected to autoimmune disorders." (PMID 40723261, 2025). "Sensitivity analyses showed no substantial changes after excluding possible new cases of autoimmune diseases and those specific autoantibodies (i.e., anti-CCP, anti-TPO, and disease specific ENA and anti-dsDNA autoantibodies) (not shown)." (PMID 31354699, 2019). "The ISPED/SIEDP suggests measuring TSH, FT4, FT3, anti TPO and anti TG in case of autoimmune disease, however without specifying when to test." (PMID 40230804, 2025). "The two patients with latent autoimmunity who have positive anti-TPO antibodies and LAC have been monitored for 9 and 6 years, respectively, without developing clinical symptoms or meeting the classification criteria for a definite autoimmune disease." (PMID 40149529, 2025). "Relevant risk factors such as thyroid peroxidase antibodies (TPOAb), TSH receptor antibodies (TRAb), thyroglobulin antibodies (TgAb), and pre-existing autoimmune diseases were not collected." (PMID 38598052, 2024). "For example, elevated thyroid peroxidase (TPO) antibodies are characteristic of Hashimoto's but do not indicate other autoimmune diseases." (PMID 39525250, 2024). "Furthermore, thyroid antibodies, predominantly anti-thyroid peroxidase (anti-TPO) antibodies, and autoimmune disorders are more commonly observed in individuals with systemic sclerosis." (PMID 38256549, 2024). "Additionally, although other autoimmune diseases related to the thyroid gland have been documented as being associated with T1D, only two patients with T1D (2.6%) demonstrated positive thyroglobulin antibody (TGAb), but were negative for thyrotrophin receptor antibodies (TRAb) and TPO antibodies." (PMID 36835954, 2023). "Notably, the thyroid peroxidase antibody level of TAO patients is significantly correlated with the disease and plays an important role in autoimmune disease." (PMID 35959376, 2022). "Because SAT is not an autoimmune disorder, high levels of anti-thyroid peroxidase antibodies (anti-TPO) or thyrotropin receptor autoantibodies (TRAb) are not expected." (PMID 35551678, 2022). "Other studies have found that taking vitamin D can reduce the titer of thyroid antibodies, especially TPO-Ab, suggesting that vitamin D may be able to affect the effect of FT4 on autoimmune diseases." (PMID 32117049, 2020).
autoimmune disease (continued). "Other confounders, in the form of age, gender, type two diabetes, smoking status, and personal and family history of autoimmune diseases did not correlate significantly with TPO Ab and Tg Ab in patients with psoriasis." (PMID 31157131, 2019). "Either form of TAI is associated with and diagnosed by the presence of anti-thyroid autoantibodies (autoantibodies targeted against one or more component of the thyroid), such as serum anti-thyroid peroxidase (TPO) and anti-thyroglobulin (Tg) antibodies even without clinical autoimmune disease." (PMID 31592370, 2019). "Given the study design and the age at recruitment, some clinical characteristics such as the frequency of autoimmune diseases or the severity of the disease could not be adequately evaluated between the anti-TPO IgE groups." (PMID 31886301, 2019). "None of anti-TPO Ab negative participants provided a positive history for autoimmune diseases." (PMID 25653881, 2015). "However, in the present study, markers of autoimmune diseases, e.g., TSH receptor antibodies or anti-TPO, were not retrieved." (PMID 35743974, 2022).